IL13RA2 (interleukin 13 receptor subunit alpha 2)
Diseases named in the same sentence as IL13RA2 in open-access papers (continued):
Sharing a sentence is not in itself a finding about the gene and the disease.
glioblastoma (continued). "Despite the encouraging evidence that supports the safety and potency of IL13Rα2-CAR T cells, the overall response of glioblastoma patients to CAR T cell therapy requires significant optimization." (PMID 30279357, 2018). "This receptor is frequently expressed on glioblastoma cells and CAR-engineered, autologous primary CD8+ T lymphocytes targeting IL13Rα2 were evaluated for treatment of recurrent glioblastoma." (PMID 30279357, 2018). "Antigen targets of interest have included interleukin-13 receptor alpha 2 (IL13Rα2) and EGFR on the basis that they are upregulated in more than 50% of glioblastoma multiforme." (PMID 28718815, 2017). "After receiving IL13Rα2-CAR T cell therapy, a patient with recurrent multifocal glioblastoma experienced dramatic improvements in his quality of life, including the discontinuation of systemic glucocorticoids and a return to normal life activities." (PMID 29312333, 2017). "The glioblastoma antigens currently targeted in the clinic, often in combination, are Cluster of Differentiation proteins (CD133, CD44 & CD70), IL receptors (IL-13Ra2), EGFR and EGFRvIII, ephrin receptor A2 (EphA2), human epidermal growth factor receptor 2 (HER2) and B7-H3." (PMID 41208963, 2025). "In glioblastoma, combinational targeting offsets antigen escape and enhances effector functions of adoptively transferred T cells, namely T cells coexpressing HER2 and IL-13Rα2-CARs." (PMID 40861448, 2025). "Targeted therapy with HER2 and EGFRvIII has improved survival in preclinical models and is expected to breach the blood‒brain barrier, whereas IL-13Rα2 and MSLN have been shown to be potential targets for tumor clearance in brain tumors such as glioblastoma (GBM)." (PMID 40850976, 2025). "A report revealed that a patient with recurrent multifocal glioblastoma who received multiple intracavitary injections of IL13Rα2-targeted CAR-T cells experienced no significant toxic side effects and obtained a significant response." (PMID 38390321, 2024). "For example, in a glioblastoma model, bispecific CAR T-cells targeting both interleukin-13 receptor subunit alpha-2 (IL-13Rα2) and ephrin type-A receptor 2 (EphA2) demonstrated enhanced efficacy and reduced antigen escape compared to single CAR bearing T-cells." (PMID 39317919, 2024). "Thus, TanCAR T-cells can enhance the control of glioblastoma multiforme through the synergistic effect of HER2 and IL13Rα2, highlighting their therapeutic potential." (PMID 38660136, 2024). "Tandem CAR-T has been developed to target HER-2 and IL13Rα2 in solid tumors, bispecific CD19/CD20 has been designed for B cell malignancies, and, more recently, a trivalent CAR T-cell construct has been developed for glioblastoma." (PMID 39770471, 2024). "Preclinical studies of glioblastoma have demonstrated that CRISPR-edited CAR-T cells targeting both Human Epidermal Growth Factor Receptor 2 (HER2) and IL13Rα2 antigens can overcome immune evasion by significantly reducing tumor growth and improving tumor control." (PMID 39871848, 2024). "For example, ligand-based IL-13Rα2-targeting CAR T cells whose binding domain utilizes a modified IL-13 ligand have shown promise for the treatment of childhood glioblastoma multiforme (GBM), resulting in tumor regression with enhanced IFN-γ signaling to activate the host immune system." (PMID 38022523, 2023). "To date, the targets of CAR-T cell therapy for glioblastoma include EGFRvIII, HER2, and IL13Rα2." (PMID 36768342, 2023). "The absence of IL13Rα2 in surrounding normal tissues has made it a suitable target in glioblastoma therapy." (PMID 35612318, 2022). "The trivalent-tandem CAR could target and recognize three different TAAs on the surface of glioblastoma cells, including human epidermal growth factor receptor 2 (HER2), interleukin-13 receptor subunit alpha-2 (IL13Rα2), and ephrin-A2 (EphA2)." (PMID 35392217, 2022).
glioblastoma (continued). "IL-13 receptor α2 (IL13Rα2) is a cancer/testis-like tumor antigen, overexpressed in multiple tumors such as CRC, renal cell carcinoma, pancreatic, melanoma, head and neck, mesothelioma, ovarian cancer and glioblastoma, among others." (PMID 33917458, 2021). "Indeed, an IL13Rα2 D1 peptide located at the IL-13 binding site showed strong inhibition capacity for the IL-13/IL13Rα2 signaling cascade in metastatic CRC and glioblastoma." (PMID 33917458, 2021). "Furthermore, a candidate IL13Rα2 therapeutic peptide was able to inhibit IL-13 signaling capacity in both tumors, CRC and glioblastoma, by inhibiting the Src pathway." (PMID 32098194, 2020). "Besides, IL-4 can also abnormally activate STAT3 in glioblastoma (GBM) cells, which are related to the expression of IL-13Rα2." (PMID 33013320, 2020). "Similarly, the inhibition of GSK-3β in glioblastoma (GBM)-specific IL13 chimeric antigen receptor expressing T (IL13-CAR-T) cells increased the survival and proliferation of CAR-positive T cells upon activation with IL13Rα2-expressing GBM tumor cells, or soluble target antigen." (PMID 32526891, 2020). "Literature review helped us identify potential binding partners (CRTH2, TMEM219, and IL13Rα2) and their expression in both non-neoplastic and glioblastoma tissue was analyzed based on data from The Cancer Genome Atlas Program (TCGA) database." (PMID 31561550, 2019). "IL-13Rα2 binds IL-13 with high affinity and has received significant attention in brain tumor therapy because it is overexpressed by high-grade glioblastomas, but not expressed at significant levels by normal brain tissue." (PMID 29168083, 2018). "IL13Rα2 has been shown to be highly expressed in many tumor types, such as colon, glioblastoma, ovarian, head and neck, kidney, and mesothelioma, but not by most normal cells such as immune cells or endothelial cells." (PMID 26418721, 2015). "Expanded ex vivo, IL13(E13Y)-zetakine+ CTL retain MHC-independent IL13Rα2-specific anti-glioma cytolytic activity, maintain CAR-regulated Tc1 cytokine secretion and proliferation, and mediate regression of established human glioblastoma xenografts in vivo." (PMID 24787244, 2014). "This circuit is primed by heterogeneous glioblastoma neo-antigens (like EGFRvIII) and subsequently eliminates target cells using tandem CARs that recognize homogenous but nonspecific antigens in glioblastoma (like EphA2 and IL13Rα2)." (PMID 40308611, 2025). "Trivalent CAR-T (HER2, IL13Rα2, and EphA2-targeted CAR-T) mediated immunoreaction forming polarized microtubule organizing centers, exhibited improved cytotoxicity and cytokine release, and overcame antigenic heterogeneity in glioblastoma thereby improving treatment outcomes." (PMID 39555054, 2024). "Targeting a tumor-restricted target such as EGFRvIII in glioblastoma via the CAR component drives localization of the cell product to the tumor enabling localized release of a TCE targeting a more homogenously expressed, yet more broadly expressed, second target such as IL13Ra2 or EGFR." (PMID 39606234, 2024). "We have recently identified PTP1B as a critical mediator in the interleukin 13 (IL-13)/IL-13 receptor α2 (IL13Rα2) pathway involved in colorectal cancer (CRC), ovarian cancer and glioblastoma (GBM) progression." (PMID 37963919, 2023). "Emerging topics in this field mainly included the study of CAR-T cells in glioblastoma (related targets: IL13Rα2, EGFRvIII, and HER2), neuroblastoma (related target: GD2), sarcoma (related target: HER2), and pancreatic cancer (related target: mesothelin), especially glioblastoma." (PMID 35371087, 2022). "Emerging topics in this field mainly include the study of CAR-T cells in glioblastoma (related targets: IL13Rα2, EGFRvIII, and HER2), neuroblastoma (related target: GD2), sarcoma (related target: HER2), and pancreatic cancer (related target: mesothelin), especially glioblastoma." (PMID 35371087, 2022).
glioblastoma (continued). "IL13Rα2 is an attractive target due to its overexpression in a variety of cancers and rare expression in healthy tissue, motivating expansion of interleukin 13 (IL13)–based chimeric antigen receptor (CAR) T cell therapy from glioblastoma into systemic malignancies." (PMID 35939683, 2022). "Emerging topics in this field mainly include the study of CAR-T cells in glioblastoma (related targets: IL13Rα2, EGFRvIII, and HER2), neuroblastoma (related target: GD2), sarcoma (related target: HER2), and pancreatic cance (related target: mesothelin), especially glioblastoma." (PMID 35371087, 2022). "Furthermore, targeting IL13Rα2 in glioblastoma using surface functionalized nanocarriers is not fully explored and needs extensive and in-depth investigation in the future." (PMID 35612318, 2022). "However, IL13Rα2 is overexpressed in a variety of tumor types such as colorectal cancer (CRC), renal cell carcinoma, pancreatic, melanoma, head and neck, mesothelioma, ovarian cancer (OC) and glioblastoma (GBM), among others." (PMID 32098194, 2020). "Our results demonstrate that the use of a Synthemax xeno-free surface enables thepropagation of glioblastoma-derived cells as a monolayer culture without serumsupplementation, and the cells were positive for the examined AAAs(IL13Rα2, Fra-1), the analysed CSCs markers and the selected markers ofEMT." (PMID 28522553, 2017). "Indeed, following cytokine stimulation, we did observe induction of a cell surface antigen on both primary glioblastoma cell lines and the monocyctic cell line THP-1, which was strongly detected by the commercially available putative IL13Rα2-targeted monoclonal antibody B-D13-PE (Cell Sciences)." (PMID 24787244, 2014). "However, in a separate study of glioma stem cells isolated from glioblastomas, IL13Rα2 expression was not reported when using the B-D13-PE antibody (Cell Sciences) (8 samples characterized)." (PMID 24787244, 2014). "The most advanced DC vaccine, ICT-107, uses autologous DC pulsed with six peptides, two HLA-A1-restricted and four HLA-A2-restricted, which derive from protein expressed and predicted to be abundant in GBM and glioblastoma cancer cells: gp100, MAGE-1, AIM2, HER2, IL13Ra2 and TRP2." (PMID 35454848, 2022). "Additionally, IL-13Rα2 overexpression correlates with advanced disease and poor prognosis in colorectal carcinoma (CRC), gastric cancer, breast cancer, clear cell ovarian cancer, lung cancer, ACC, papillary thyroid cancer, pancreatic ductal adenocarcinoma, and glioblastoma (GBM)." (PMID 35464460, 2022). "We previously identified IL13RA2 as an attractive molecular target that is highly overexpressed in glioblastoma (GBM) but not in normal brain." (PMID 28881623, 2017). "Our results illustrate a relationship between high IL-13Rα2 expression and poor prognosis in patients diagnosed with ACC in agreement with our previous observations in patients with human glioblastoma multiforme (GBM) which also utilized the NCI’s TCGA database." (PMID 33591997, 2021). "Currently, phase I studies combining anti-EGFRvIII CAR-T cells with pembrolizumab (NCT03726515) and anti-IL-13Rα2 CAR-T cells with or without ipilimumab and nivolumab (NCT04003649) are now recruiting patients with glioblastoma." (PMID 32235752, 2020). "In one patient with recurrent multifocal glioblastoma, intracranial administration of IL-13Rα2-targeted CAR T cells resulted in the regression of all intracranial and spinal lesions, but subsequent relapse was in IL-13Rα2-negative tumors." (PMID 37165457, 2023). "The radiolabeled IL13Rα2-CAR-T and PSCA-CAR-T cells were administered to glioblastoma- and prostate cancer-bearing nonobese diabetic severe combined immunodeficient (NSG) mice, respectively, and they were visualized by PET/CT imaging with relatively high specificity." (PMID 34093854, 2021).
glioma (148 papers, 2007 to 2026). A benign or malignant brain and spinal cord tumor that arises from glial cells (astrocytes, oligodendrocytes, ependymal cells). "Examples of TAAs targeted in pediatric glioma vaccines include the cytomegalovirus (CMV) pp65 antigen and glioma-associated antigens (GAAs) such as EphA2, IL13RA2, and Survivin." (PMID 41441679, 2025). "Research has identified several glioma‐associated antigens, such as IL13Ra2 and EGFRvIII, that can be targeted using mRNA vaccines." (PMID 40948290, 2025). "We developed a fully immunocompetent, genetically engineered mouse model (GEMM) for pDMG and pHGG that incorporates the glioma-associated antigen, IL13RA2 and demonstrated the suitability of the model for evaluation of targeted therapy such as CAR T cells." (PMID 39711568, 2024). "To achieve this, we developed a fully immunocompetent, genetically engineered mouse model (GEMM) for pDMG and pHGG that incorporates the glioma-associated antigen, interleukin 13 receptor alpha 2 (IL13RA2)." (PMID 39711568, 2024). "One of the challenges of successful IL-13Rα2 target therapy, is the loss of a targeted antigen with treatment and intra-glioma heterogeneity." (PMID 37158824, 2023). "In summary, our findings demonstrated that IL-13Rα2 expression was significantly associated with cytoplasmic distribution of FUS in human glioma samples." (PMID 37158824, 2023). "IL-13Rα2 is one of the most widely studied tumor-associated antigens in glioma research, which is also overexpressed in a variety of solid cancers, including gliomas, melanoma and pancreatic, ovarian, breast, colon and prostate cancers." (PMID 37158824, 2023). "Unfortunately, despite enhanced recognition of glioma cells, greater proliferative capacity and increased production of cytokines, the improved T cell persistence was associated with recurrence of gliomas with down-regulated IL-13Rα2 expression." (PMID 35211124, 2022). "Alternatively, glioma tumor cells produce IL-13, which in turn caused autocrine activation of cell signaling through AP-1 pathway by engaging IL-13Rα2 chain." (PMID 30572904, 2018). "Recently, an inspiring case report showed regression of all intracranial and spinal tumors for a patient with recurrent multifocal glioblastoma who received CAR T cells targeting glioma-associated antigen interleukin-13 receptor alpha 2 (IL13Rα2)." (PMID 28434147, 2017). "IL-13Rα2 is selectively expressed on glioma cells and associated with increased malignant grade and poor patient prognosis." (PMID 28752098, 2017). "In contrast, silencing of IL-13Rα2 in EGFRvIII-positive glioma cells and primary culture caused a significant reduction in STAT3 activation." (PMID 29203859, 2017). "GBM patients vaccinated with autologous dendritic cells pulsed with different glioma-associated tumor antigens, including IL13Rα2, have shown significant prolongation of progression-free survival." (PMID 25247196, 2014). "IL13Rα2-targeting CARs have also been successful against chemo- and radioresistant glioma-initiating cells which otherwise are the cause of recurrent GBM." (PMID 25247196, 2014). "Further, IL13Rα2 expression increases with glioma malignancy grade and is associated with decreased long-term survival, a single gene correlation stronger than seen for the mesenchymal signature genes." (PMID 24204956, 2013). "Further we find that IL13Rα2 expression increases with glioma malignancy grade, is linked to activated immune pathways by IPA analysis, and is a prognostic indicator of poor patient survival." (PMID 24204956, 2013). "IL-13Rα2 is one of the most widely studied tumor-associated antigens in glioma research." (PMID 37158824, 2023).
glioma (continued). "However, most recent clinical trials evaluate efficacy of DCs pulsed with IL-13Rα2 antigen and other glioma-associated peptides." (PMID 35464460, 2022). "The treated glioma cells were associated with high expression of IL13Rα2 levels." (PMID 35612318, 2022). "Preclinical mouse models showed that IL13Rα2 CAR T could cause regression of adult glioma patient-derived xenografts (PDX), including tumours derived from intracranial injection of a stem-cell enriched population." (PMID 36505819, 2022). "We and others have shown that IL-13Rα2 may be associated with the increase in glioma malignancy grade and associated with poor patient prognosis." (PMID 29168083, 2018). "IL-13Rα2 expression was significantly associated with cytoplasmic distribution of FUS in human glioma samples and could be the independent prognostic factors for OS, while the prognostic value of its co-expression with cytoplasmic FUS in glioma need to be addressed in the future studies." (PMID 37158824, 2023). "For instance, IL-13 or IL-4 cytokines fused to bacterial toxins can direct cytotoxic payloads to glioma cells overexpressing IL-13Rα2 or IL-4R." (PMID 40918539, 2025). "The results indicated that these vNARs had a significant capability to inhibit both the growth and migration of high IL-13Rα2 expressive glioma cells by hindering IL-13Rα2 on the cell surface." (PMID 39940647, 2025). "EGFRvIII, EGFR, and HER2 are more frequently expressed in adult gliomas, while IL13Rα2, B7-H3, and GD2 appear to be suitable candidates for both adult and pediatric CNS tumors." (PMID 40895575, 2025). "Interleukin-13 receptor alpha 2 (IL-13Rα2) is another compelling target for glioma conjugate therapy." (PMID 40918539, 2025). "Recently, a study assessed anti-IL-13Rα2 vNARs from an immune library from Chiloscyllium plagiosum (whitespotted bamboo shark) in A172 glioma cells." (PMID 39940647, 2025). "IL-13Rα2 not only enhances the invasiveness of glioma cells but also promotes tumor cell proliferation in the presence of the mutant epidermal growth factor receptor (EGFRvIII)." (PMID 40142943, 2025). "IL13RA2 inhibition has resulted in tumor regression in murine models of glioma and colorectal cancer." (PMID 40663259, 2025). "In preclinical models of GBM, CAR-T cells have demonstrated robust antitumor activity and are currently being evaluated in phase I/II studies targeting glioma-specific, antigens IL-13Rα2, HER2, and EGFR." (PMID 40092990, 2025). "IL13RA2 was first of interest because of its elevated, tumor-specific expression pattern in gliomas." (PMID 40663259, 2025). "Subsequent methods using extracellular toxins specifically targeting IL13Ra2 show certain anti-glioma activities with enhanced specificity and minimal neurotoxicity." (PMID 38201655, 2024). "This line has been further engineered to express the murine IL13Rα2 and used to recapitulate invasive glioma in syngeneic mouse models." (PMID 38449858, 2024). "While these techniques are still in their exploratory stages, the potential value of targeting IL13Ra2 for glioma therapy is undeniable." (PMID 38201655, 2024). "Mounting evidence has shown an overexpression of IL13Ra2 in a fraction of supratentorial gliomas, especially in GBMs." (PMID 38201655, 2024). "Investigations have focused on a hybrid cytolytic peptide, comprising a unique receptor-binding domain (Pep-1) and a cytolytic domain (Phor21), tested against gliomas expressing IL-13Rα2." (PMID 38612592, 2024). "To understand the effect of ICG-001 on tumor metabolism alone and in combination with IL13Rα2–CAR T cells, we established orthotopic immunocompetent mouse models of syngeneic glioma using K-Luc glioma cells and engineered murine IL13Rα2-targeted CAR T cells." (PMID 38449858, 2024). "While a transient reduction in glioma activity was noted in two patients, examination of tumor tissue from one patient indicated a decrease in overall IL13Rα2 expression." (PMID 38727262, 2024).